CD83 (CD83 molecule)
Description:
Transmembrane glycoprotein predominantly found on the surface of many immune cells including dendritic cells or lymphocytes that plays various roles in immune response regulation. Plays an essential role in CD4(+) T-selection, differentiation and stability by regulating the activity of the major E3 ubiquitin ligase responsible for controlling MHCII trafficking MARCHF8. Also inhibits MARCHF1 association with MHCII or CD86 to prevent their ubiquitination and subsequent degradation. In addition, acts as an important modulator of protective responses against acute infections (By similarity).
Synonyms: HB15; BL11
Tractability: Antibody: its Gene Ontology location is reachable by antibodies, with high confidence; UniProt predicts a signal peptide or a membrane-spanning region; the Human Protein Atlas places it where antibodies can reach. PROTAC: ubiquitination databases record sites on it.
Gene: Protein-coding gene on chromosome 6 (14,117,256 to 14,140,682, forward strand). Ensembl gene ENSG00000112149.
Subcellular location: Membrane
Subcellular location (Human Protein Atlas): Nucleoplasm; Plasma membrane; Golgi apparatus; Nucleoli
Gene Ontology:
Molecular function: protein binding; ubiquitin ligase inhibitor activity
Biological process: defense response; humoral immune response; signal transduction; production of molecular mediator involved in inflammatory response; regulation of interleukin-4-mediated signaling pathway
Cellular component: plasma membrane; external side of plasma membrane; membrane
Genetic constraint (gnomAD): Loss-of-function variants: 14 observed, 15.82 expected, observed/expected ratio (o/e) 0.89, 90% interval 0.58 to 1.38. The upper end of that interval is the gene's LOEUF score, 1.38, which puts it in group 5 of 6, group 1 being the genes least tolerant of losing a copy. Missense variants: 208 observed, 204.02 expected, observed/expected ratio (o/e) 1.02, 90% interval 0.91 to 1.14. Synonymous variants: 86 observed, 86.31 expected, observed/expected ratio (o/e) 1, 90% interval 0.84 to 1.19.
Homologues: Orthologues: chimpanzee CD83 (99% identical), macaque CD83 (98% identical), guinea pig CD83 (78% identical), rabbit CD83 (77% identical), pig CD83 (72% identical), dog CD83 (68% identical), rat Cd83 (67% identical), mouse Cd83 (66% identical).
Diseases named in the same sentence as CD83 in open-access papers:
CD83 is named in the same sentence as 164 diseases in open-access papers, as found by Europe PMC text mining. Sharing a sentence is not in itself a finding about the gene and the disease. The quoted sentences say what the papers report.
melanoma (22 papers, 2002 to 2024). A malignant, usually aggressive tumor composed of atypical, neoplastic melanocytes. "Flow cytometry assays indicated that G34E variant was associated with upregulation of CD83 in human melanoma cell lines." (PMID 32708981, 2020). "Data analysis based on clinical data also showed that patients exhibiting elevated levels of CD83 in the context of mUC, mGC, NSCLC, CLL, and melanoma demonstrated heightened susceptibility to immune checkpoint inhibitors." (PMID 38653742, 2024). "Considering that DCs and LCs, in particular, are promising targets for future immunotherapeutic strategies, IDO and its correlation with CD83 have been widely investigated in SLN LCs of melanoma patients." (PMID 38791968, 2024). "Even SLN Langerhans cells (LCs), the typical DC subset of epithelia, show an immature immunophenotype, with low levels of CD83 expression, the DC maturation marker, particularly in melanoma bearing SLNs." (PMID 35408802, 2022). "Since LCs are a promising target for cancer immunotherapy we aimed to investigate the expression of IDO1 in SLN LCs of patients with melanoma, correlating it with CD83 and with clinical features of patients." (PMID 35408802, 2022). "Consistent with the idea that CD83 is downstream of NFkB and can be affected by NFKBIE variants in melanomas, human melanoma cell line with G34E variant, A375, displayed TNFalpha-induced CD83 expression, compared to melanoma cell line with WT variant, SKEML28." (PMID 32708981, 2020). "Mechanistically, TEX-derived miR-4498 decreases CD83 levels, thereby impairing immune system responses against melanoma cells." (PMID 29652798, 2018). "This is in accordance with a recent study suggesting that melanoma Mo-MDSCs express high levels of CD83." (PMID 25992611, 2015). "Immature DCs efficiently phagocytosed melanoma Apo-Nec cells and matured after phagocytosis as evidenced by increased expression of CD83, CD80, CD86, HLA class I and II, and 75.2 ± 16% reduction in Dextran-FITC endocytosis." (PMID 18221542, 2008). "Previously, we have reported that the in vitro stimulation with the melanoma cell lysate TRIMEL to primary human AM cells mediated up to four-fold induction of several surface markers associated with DCs maturation such as MHC-I, MHC-II, CD80, CD83, and CD86." (PMID 35805888, 2022). "LCs in SLN of patients with melanoma shows an immature immunophenotype, with low CD83 expression." (PMID 35408802, 2022). "Next, we investigated IDO1 and CD83 co-expression in SLN LCs from patients with melanoma." (PMID 35408802, 2022). "Subsequently, we investigated whether LCs from melanoma SLNs were still able to reach a mature immunophenotype with CD83 up-regulation by fluorescent immunocytochemistry and flow cytometry (n = 5 negative SLNs from n = 5 patients)." (PMID 35408802, 2022). "Similarly, exosomes released by hypoxic melanoma cells express miR-4498, which regulates CD83, an immunostimulatory molecule that is critical for T cell activation." (PMID 29652798, 2018). "DCs matured in vitro in the presence of melanoma EVs demonstrated significantly impaired expression of CD83 and CD86 as well as decreased expression of Th1 polarizing chemokines Flt3L and IL15 and migration chemokines MIP-1α and MIP-1β compared to liposome-treated DCs." (PMID 28424693, 2017). "However, the percentage of CD83+ DCs matured from melanoma-patient derived cells was lower than in identically treated cells derived from patients suffering from chronic myelogenous leukemia." (PMID 16911798, 2006). "Consequently, tolerogenic immature IDO1+CD83-LCs could be involved in LNs metastasis arrival/homing and melanoma proliferation." (PMID 38791968, 2024). "However, the CD83 maturation marker was expressed in a considerably lower percentage (16.68 ± 7.73% vs. 45–50%), suggesting that melanoma patients’ LCs migrate from the skin to SLNs, preserving immature phenotype, possibly tolerating melanoma-associated antigens and promoting cancer spread." (PMID 38791968, 2024).
melanoma (continued). "We have previously reported that the addition of the heat shock-conditioned melanoma lysate TRIMEL to IL-4/GM-CSF-activated monocytes (AM) mediates the induction of canonical surface markers associated with DC maturation such as MHC I, MHC II, CD80, CD83, and CD86." (PMID 31886313, 2019). "The CD83 molecule, a marker of DC mature immunophenotype, is poorly expressed by SLN LCs of melanoma patients, possibly explaining their inability to stimulate anti-melanoma immunity." (PMID 38791968, 2024). "Then, CD83+ LCs, IDO1+/− (real mature SLN LCs and regulatory/inhibitory SLN LCs) migrate to SLN, possibly modulating the escape mechanism in melanoma." (PMID 38791968, 2024). "SLN LCs in patients with melanoma are functionally defective (low CD80/86 co-stimulatory molecules), immature (low CD83), and express IDO enzymes." (PMID 38791968, 2024). "Consistent with a previous study on melanoma patients, we detected variable level of CD80, CD83 and/or CD86 expression on CD14+HLA-DR−/low MDSC in the PB and/or ascites from OC; however, their functional significance remains elusive." (PMID 29100353, 2017). "This hypothesis might be consistent with the frequencies detected for the four SLN LCs subsets in melanoma patients, being CD83+IDO1- and CD83-IDO1- the main SLN LCs subsets, and CD83+IDO1+ SLN LCs, the lower one, slightly affected by melanoma." (PMID 38791968, 2024). "In a previous study on 12 types of malignant neoplasms (breast, lung, colon and melanoma), including a case of adenoid cystic carcinoma, no immunoexpression of CD83 was reported." (PMID 37992142, 2024). "In order to better understand SLN LCs functional properties, the Authors focused on LCs IDO1 and CD83 relative expression in both melanoma-positive and negative SLNs." (PMID 38791968, 2024). "The CD83 down-regulation and IDO1 expression might be induced by melanoma and represent a novel immuno-escape mechanism." (PMID 35408802, 2022). "Interestingly, expression of costimulatory markers CD83 and CD86 were significantly decreased in DCs treated with melanoma-derived EVs compared to either liposome-treated DCs or DCs alone." (PMID 28424693, 2017). "Three different DC lines cultured for 7–9 days in medium containing GM-CSF and IL-4 (CD14−, CD36+ and CD83−) showed higher levels of intracellular MC1R than short time cultured monocytes, comparable to that observed in the low MC1R expressing BL melanoma cell line." (PMID 12177778, 2002). "Additionally, melanoma-induced IDO1 expression and CD83 downregulation could represent a new tumor escape mechanism." (PMID 38791968, 2024). "Furthermore, positive SLNs hosted lower levels of mature CD83+ LCs compared to melanoma-negative SLNs (40.51%), confirming previous reports." (PMID 38791968, 2024). "Furthermore, CD36 and CD83 expressions were detected in human melanoma cells, but we were not able to confirm it in our studies." (PMID 34885093, 2021). "Moreover, the authors questioned whether the melanoma-positive SLN LCs group by Gerlini expressed lower levels of CD83 due to the higher Breslow thickness (mean 3.21 mm) rather than melanoma in the SLN." (PMID 38791968, 2024). "Furthermore, CD80, CD83, and CD86 expression on DC was decreased upon co-culture with melanoma cells and could be partially restored with BRAF inhibition in BRAFV600E mutant melanoma cell lines." (PMID 24194739, 2013). "They revealed that both melanoma-negative and positive SLN LCs expressed lower levels of CD83, CD80, CD86, and HLA-DR (maturation markers) compared to epidermal explant–migrated (mature) LCs." (PMID 38791968, 2024). "IDO1, expressed by both LCs and melanoma cells, lead to the production of KYN, which directly stimulate LCs to express more IDO1 trough AhR without inducing CD83 expression." (PMID 35408802, 2022).
melanoma (continued). "DC co-cultured with melanoma cells alone did not present significant phenotypic characteristics of DC maturation (CD80: ~5%, CD83: ~6%, CD86: ~10%), and co-culture with UV-irradiated apoptotic cells led to a non-significant increase of CD83 markers only (~11%)." (PMID 22029859, 2011). "Consequently, increased IDO1 expression in both APCs and melanoma cells could promote KYN-AhR interactions, stimulating peripheral LC and leading to a vicious cycle with further LCs IDO1 expression, but without improving CD83 expression." (PMID 38791968, 2024).
breast carcinoma (20 papers, 2002 to 2026). "In breast cancer, mature DCs detected by the CD83 or DC-LAMP marker were present in lower amount in tumor-positive SLNs compared to tumor-negative ones while the density of DCs stained for CD1a was similar." (PMID 23418928, 2013). "In breast cancer, blood DC exhibit an altered phenotype with increased level of CD83 and this correlated with disease severity." (PMID 20976171, 2010). "Of note, a partial mature blood DC phenotype, with elevated CD83 expression, correlated with the severity of breast cancer." (PMID 20976171, 2010). "This study investigates the expression of the epithelial DC marker CD1a with that of CMRF-44, CMRF-56 and CD83 to determine the activation state of DC in human breast cancer." (PMID 11870535, 2002). "Similarly, in a study examining the role of DC maturation status in patients with breast cancer, CD83 expression was prognostic for overall and relapse free survival whereas CD1a, a marker of immature DC, was not." (PMID 29872507, 2018). "Furthermore, STF noticeably induced several gene expressions associated with breast cancer anti-estrogen resistance 3 (BCAR3), cluster of differentiation 83 (CD83), nucleotide-binding oligomerization domain containing 2 (NOD2)." (PMID 28068976, 2017). "However, we observed a slight increase in the expression of CD83 in HLA-DRlow/- monocytes from breast cancer patients." (PMID 25992611, 2015). "Though the antigen presenting ability of these cells is not known, in human breast cancer specimens, increased CD83+ dendritic cells is associated with an improved prognosis." (PMID 19888452, 2009). "DC maturation appeared correlated to the clinical stage of disease, since the percentage of CD83+ DCs tended to increase progressively with the severity of breast cancer (carcinoma in situ: 4.31 ± 0.81; stage I: 4.91 ± 2.00; stage IIA: 5.11 ± 1.05; stage IIB: 5.46 ± 0.83)." (PMID 14562018, 2003). "To assess the ability of PB DCs from breast cancer patients to be activated following stimulation, we exposed whole-blood samples to LPS for 5 h, and subsequently analysed the expression of costimulatory molecules and CD83 on DCs." (PMID 14562018, 2003). "Otherwise, analysis of the maturation state of Lin-/HLA-DR+ DCs, evaluated as the expression of CD83 molecule, showed that breast cancer patients had a significantly higher percentage of mature CD83+ DCs compared with control subjects (5.23±0.57 vs 3.00±0.75%; P=0.019)." (PMID 14562018, 2003). "The high percentage of Lin-/HLA-DR+ DCs expressing CD83 observed in breast cancer patients could be induced by tumour-derived factors, as suggested by the observation that the increased expression of CD83 by PB DCs was completely reverted in our patients 4 weeks after surgical removal of the tumour." (PMID 14562018, 2003). "that NDV infected MCF-7 cells have beneficial effects on the antigen presentation capacity of breast cancer patient derived dendritic cells demonstrated by an upregulation of CD40, CD80, CD83, CD86 and MHC class II (HLA-DR)." (PMID 34777344, 2021). "This study aimed to investigate the density of DCs expressing CD1a, CD83, CD123, DC-LAMP3 (CD208) and DC-SIGN (CD209) in breast cancer." (PMID 33919875, 2021). "The aim of the present study was to investigate the density of DCs expressing CD1a, CD83, CD123, DC-LAMP3 (CD208) and DC-SIGN (CD209) in breast cancers." (PMID 33919875, 2021). "This study showed that LPS-stimulated human dendritic cells (DCs) decreased the expression of HLA-DR, CD83 and costimulatory molecules (CD40, CD80 and CD86) following coculturing with CTLA-4+ breast cancer cells." (PMID 28099147, 2017). "We used CD1a as a marker of immature DCs, CD83 as a marker for mature DCs, CD3 as a marker for T cells, and pan-cytokeratins as a marker for breast cancer cells." (PMID 24088396, 2013).
breast carcinoma (continued). "In vivo validation using immunohistochemistry on clinical samples from 10 breast cancer patients with ovarian metastases confirmed that GPR183, BHLHE41, and CD83 were highly expressed in tumor tissues, while SLC25A37 and SELL were highly expressed in adjacent normal tissues." (PMID 42101520, 2026). "In breast cancer, the number of CD83+ mature DCs, but not the number of CD1a+ or S100+ DCs, has been shown to be of prognostic relevance." (PMID 20969772, 2010). "Unlike other myeloid cell types, increased tumor-infiltrating DCs is associated with improved prognosis and specifically, the number of CD83+ DCs has been shown to inversely correlate with lymph node metastasis and tissue expression of VEGF and TGF-β in human breast cancer specimens." (PMID 19888452, 2009). "Interestingly, CD83+ DCs have been described in the peritumoral areas of breast cancer samples, while absent in the normal breast tissue." (PMID 14562018, 2003). "Our previous work in breast cancer patients has clearly demonstrated that such DCTs and DCTIs have an optimal antigen uptake capacity and upregulation of CD86, CD40 and class I, but low levels of CD83, as is expected of non-terminally mature DCs." (PMID 19298672, 2009).
colitis (14 papers, 2013 to 2025). Inflammation of the colon. "Their results showed that loss of CD83 in DC would lead to the worsening and acutisation of the inflammation level in colitis model." (PMID 38610835, 2024). "An overexpressed CD83 on the mucosal surface “protects” from colitis, while loss of expression of CD83 in DC worsens the colitis." (PMID 38610835, 2024). "In the colitis mice model, CD83 marker expression in DCs was downregulated and caused the inflammation to worsen." (PMID 36769151, 2023). "Their results showed that loss of CD83 in DCs led to worsening of inflammation in the colitis model." (PMID 32572123, 2020). "On the other hand, mice with a conditional knockout of CD83 in DC exhibited increased susceptibility to severe colitis, further indicative of a role for CD83 in DC regulation." (PMID 31231400, 2019). "In PPs, administration of the probiotic mixture to mice with colitis significantly decreased the frequencies of CD83+ (p < 0.05), CD86+ (p < 0.01), and CD11c+ cells (p < 0.01) compared to untreated colitis mice." (PMID 39201260, 2024). "Parallel to this, it has been discovered that Tetragenococcus halophilus, a lactic acid-producing bacterium, can suppress DSS-induced colitis in mice exhibiting increased CD83 molecule expression." (PMID 36769151, 2023). "Used lamina propria of CD83 knockdown mice that develop worsened colitis using dextran sodium sulfate (DSS)." (PMID 36769151, 2023). "In vivo, CD83+ T cells inhibit colitis symptoms in a colitis model by suppressing inflammatory cytokines and the release of sCD83." (PMID 36769151, 2023). "The first study has revealed that specific deletion of CD83 expression in DCs aggravates disease symptoms in chemical- and bacterial-induced colitis models." (PMID 35054916, 2022). "The frequencies of CD83+ cells in colitis mice were also significantly increased compared with T. halophilus treated normal mice in IELs (67.92 ± 1.10% vs. 49.06 ± 3.11%, p < 0.001)." (PMID 35741032, 2022). "More extensive analyses of CD83-expressing T cells revealed that CD83+/CD4+ T cells selectively express high levels of Treg associated surface markers and conferred immunosuppression in a transfer colitis model." (PMID 35054916, 2022). "A significant number of DCs expressing CD83 molecules have been observed in CD patients and murine colitis models." (PMID 35741032, 2022). "Soluble CD83 has been suggested to have therapeutic and immunosuppressive properties by suppressing DCs-mediated T cell activation and ameliorating experimental colitis in mice." (PMID 35741032, 2022). "Frequencies of CD83+ cells were significantly increased in colitis mice compared to normal control mice in PBL (39.88 ± 8.91% vs. 25.70 ± 2.36%, p < 0.05) and compared to normal mice treated with T. halophilus (39.88 ± 8.91% vs. 16.70 ± 3.60%, p < 0.001)." (PMID 35741032, 2022). "CD83, a specific marker of dendritic cells (DCs) for antigen presentation and lymphocyte activation, can regulate immune responses to prevent colitis by regulating DC surface proteins." (PMID 32153632, 2020). "The induction of colitis is characterized by a reduced number of mature CD11c+CD83+ dendritic cells (DCs) in the periphery and spleen and by a raised level in the mesenteric lymph nodes." (PMID 23425343, 2013). "Just as whole BC is effective in preventing DSS-induced colitis, so sIgA treatment was characterized by massive increases in colonic CD11c+ and CD83+ DCs as well as γδ TCR+ T cells." (PMID 23425343, 2013). "However, CD83 DCs overexpression on the mucosal surface can protect against colitis, demonstrating the functional aspect of CD83 upon DCs in immunological homeostasis." (PMID 36769151, 2023). "A reduction in CD83 DCs levels can worsen the inflammation in the colitis model." (PMID 36769151, 2023). "Expression level of CD83 marker is significantly higher in DSS-colitis mice." (PMID 36769151, 2023).